GFAP (glial fibrillary acidic protein)
Diseases named in the same sentence as GFAP in open-access papers (continued):
Sharing a sentence is not in itself a finding about the gene and the disease.
glioblastoma (continued). "Besides, side populations of glioblastoma cells (U251 and primary glioblastoma sample) were less sensitive to HSV-TK/GCV system than the non-side population, indicating that GFAP-positive cells may not be fully ablate under GCV treatment in our study." (PMID 34370752, 2021). "In contrast, in human glioblastoma (GBM) cell lines CA did not down-regulate the PI3K/AKT pathway, whereas it induced proteasomal down-regulation of Retinoblastoma, Cyclin B1, SOX2 and GFAP and cell cycle arrest with only a minor induction of apoptosis." (PMID 29100552, 2017).
ischemia (170 papers, 2010 to 2026). A hypoperfusion of the BLOOD through an organ or tissue caused by a PATHOLOGIC CONSTRICTION or obstruction of its BLOOD VESSELS, or an absence of BLOOD CIRCULATION. "Ischemia was associated with a decrease in the area fraction of GFAP in all regions compared with sham control (P < 0.001, P = 0.030, P = 0.02 in the IGWM1, IGWM2, and PVWM respectively)." (PMID 39103629, 2025). "In the present study, ischemia was associated with a significant increase in the number of GFAP+ astrocytes but decrease in area fraction of labeling at 7 days." (PMID 39103629, 2025). "Here we used a mouse model of genetically attenuated reactive gliosis (mice deficient for IF proteins GFAP and vimentin) to determine the impact of ischemia-induced reactive gliosis on the regenerative capacity of transplanted human iPSC-derived NSPCs." (PMID 29401502, 2018). "GFAP is an intermediate filament protein, and its over-expression has been associated with ischemia and retinal degeneration." (PMID 23610595, 2013). "Numerous retinal damaging factors, including ischemia, cause elevated GFAP expression." (PMID 39125579, 2024). "Furthermore, red light alleviates the damage caused by ischemia and reduces glial fibrillary acidic protein (GFAP), associated with the stress response." (PMID 36829717, 2023). "In ischemia-associated astrocytic plasticity, abnormal activity of glial fibrillary acidic protein (GFAP) and aquaporin 4 (AQP4) may play essential roles in abnormal neuronal activity or neural damages." (PMID 32985231, 2020). "Moreover, vimentin/glial fibrillary acidic protein (GFAP) immunolabelling of Müllers is elevated after ischemia; this is also associated with a reduction in RGC numbers." (PMID 29933759, 2018). "This change was probably caused by ischemia‐induced activation of the GFAP promoter." (PMID 28370368, 2017). "Notably, both promoters were activated by ischemia and caused a parallel increase of transcripts encoding GFAP and dnSNARE/EGFP." (PMID 28370368, 2017). "GFAP, a marker for reactive gliosis, reflects Muller cell activation caused by RD-induced ischemia." (PMID 22899456, 2013). "S100b levels are higher at least 48 h after the onset of cerebral ischemia, whereas GFAP levels increase sooner after ischemia onset, making it a more suitable biomarker for early diagnosis." (PMID 40863995, 2025). "In vitro studies also show that C3a treatment improves astrocyte survival and reduces the expression of GFAP following ischemia." (PMID 41002405, 2025). "GFAP is a structural component of intermediate filaments in the astrocyte cytoskeleton, and GFAP production is upregulated after ischemia, which is considered a neuroprotective mechanism." (PMID 36927495, 2023). "Blood GFAP levels are correlated with the clinical severity and extent of intracranial pathology in spinal cord disorders, acute CNS trauma, ischemia, neurodegenerative diseases, malignant brain tumors, and cerebrovascular events." (PMID 37174709, 2023). "Exercise increased the population of GFAP-positive astrocytes born between POD0 and 3 on POD15 while ameliorating ischemia-induced dendritic spine loss on POD15." (PMID 36880055, 2023). "This was examined further in the oxygen–glucose deprivation (OGD) model of ischemia, where EDAC caused an increase in astrocytic process branching, resulting in an increase in GFAP-EGFP." (PMID 37170258, 2023). "This leads to a more rapid increase with higher concentrations of GFAP in intracranial haemorrhage than in ischemia." (PMID 37511304, 2023). "Triggers that upregulate the expression of GFAP include brain injury, neuroinflammation, ischemia, infection, neurodegenerative diseases, and other insults that lead to astrocyte activation or reactive gliosis." (PMID 37822710, 2023).
ischemia (continued). "In the current study, the dual-IF staining showed that, cerebral ischemia induced a strong increase in the number of A1 (C3 + GFAP +) subtype astrocyte in the penumbra, with the effect reaching maximal level at day 14 post-ischemia." (PMID 36823628, 2023). "In the ischemia group, GFAP immunoreactive astrocytes showed an active form that possessed hypertrophic cytoplasm." (PMID 36835378, 2023). "In this study, brain injury was assessed by expression of pro-inflammatory cytokines and GFAP after 24 h of reperfusion in IR mice where Hcy were treated immediately after ischemia." (PMID 36551804, 2022). "GFAP area fraction was restored in the ischemia-hypothermia group to sham control levels (p = 0.128)." (PMID 35690757, 2022). "Inflammatory activation within the core border of GFAP- and Iba-1-expressing astrocytes and microglia demonstrates the importance of this region early after ischemia." (PMID 36151369, 2022). "In the intragyral white matter of the sagittal and the first and second parasagittal gyri, GFAP area fraction was less in the ischemia-normothermia group, than in sham controls (p = 0.001)." (PMID 35690757, 2022). "The ischemia-induced increase of glial fibrillary acidic protein (GFAP; a maker of astrocyte) expression in severe ischemia was significantly higher than that in mild ischemia." (PMID 35563487, 2022). "Regarding microglia and astrocytes, visualized by Iba, GFAP, and AQP4, the observed ischemia-associated alterations were in line with earlier reports exploring cellular changes due to ischemia." (PMID 35682557, 2022). "The area fraction of GFAP in the cortex of the sagittal and the first and second parasagittal gyri was greater in the ischemia-normothermia group than sham controls (p = 0.001)." (PMID 35690757, 2022). "We investigated the potential treatment effect of short-term CSF-1R inhibition on (GFAP-positive) astrocytes on days 14 and 35 after ischemia." (PMID 35115368, 2022). "The brains were double stained for TSPO and Iba-1 or GFAP or F4/80 at day 35 post ischemia to identify the cellular sources of TSPO." (PMID 33754046, 2021). "In the Normo + ischemia group, GFAP immunoreactive astrocytes positive for HO-1 were rarely observed in the SP at 12 h after ischemia." (PMID 33921375, 2021). "Astrocyte marker glial fibrillary acidic protein (GFAP) was also stained to indicate the ischemic core, as astrocytes form glial scar in the perilesional area after ischemia." (PMID 34154653, 2021). "With time after ischemia, GFAP immunoreactive astrocytes became hypertrophied, and their cellular processes became thickened in both of the ND and IF/ischemia groups." (PMID 33440708, 2021). "As a result of ischemia, astrocytes release vimentin, nestin, IL-1β, monocyte chemotactic protein-1, and glial fibrillary acidic protein, which contribute to the development of reactive gliosis and the formation of glial scars after ischemia." (PMID 33922467, 2021). "Vimentin and GFAP are intermediate filaments involved in neural plasticity and regeneration and play important roles in responses to stress such as injury, ischemia and neurodegeneration." (PMID 33504361, 2021). "On the other hand, after ischemia, the pattern of changes in the GFAP immunoreactive astrocytes was similar between the ND and IF groups." (PMID 33440708, 2021). "In our current study, HO-1 immunoreactivity was shown early and significantly increased in NeuN immunoreactive pyramidal neurons and GFAP immunoreactive astrocytes in CA1–3 of the Hyper + ischemia group when compared with that in the Normo + ischemia group." (PMID 33921375, 2021). "Astrocytes are known as crucial brain mediators capable of releasing several pro-inflammatory factors following ischemia, including intermediate-filament and glial fibrillary acidic protein (GFAP)." (PMID 32963745, 2020). "In our ischemia reperfusion model, the expression of Iba1 mRNA nearly doubled in the ipsilateral hemisphere together with GFAP." (PMID 33057165, 2020).
ischemia (continued). "As a net result, the percentage of GFAP+/IGF-1+ double-positive cells among the GFAP+ astrocytes was significantly increased from 50.79 ± 8.97% in the ischemia control group to 78.70 ± 20.11% in the MSC group." (PMID 32952570, 2020). "This perspective is supported by studies that identified serum markers of the NVU like GFAP, allowing insights into local processes of the ischemia-affected brain." (PMID 33192578, 2020). "Following MSC treatment, the number of GFAP+ astrocytes (42.3 ± 5.2/view field) was slightly but significantly reduced compared to that in the ischemia control group (48.43 ± 9.67/view field)." (PMID 32952570, 2020). "This suggests that CP epithelial cells have also neural stem cell characteristics with the ability to express neuronal nuclear protein (NeuN) and glial fibrillary acid protein (GFAP) after mild to severe ischemia." (PMID 32375819, 2020). "Microglia release cytokines that influence the activation of GFAP+ cells resulting in glial scar formation and are critical for neuron-glial communication after ischemia." (PMID 33551749, 2020). "A2AR selective antagonist SCH58261 has been revealed to decrease GFAP expression in rat brain astrocyte cell line with ischemia-like injury." (PMID 32714489, 2020). "In the vehicle/ischemia group, GFAP immunoreactive astrocytes were hypertrophied, and their processes were thickened." (PMID 31940961, 2020). "In the usnic acid-treated group, the GFAP-positive cell rate was decreased (54.86%±7.33) compared with the ischemia group (P<0.001)." (PMID 32963745, 2020). "The cytokine is detected in GFAP-positive cells in healthy controls and shows a gradual increase after ischemia, with a punctate labelling pattern in the cell body and along astrocytic main processes (as seen in single-plane confocal images)." (PMID 30679481, 2019). "At 5 days post-TGCI in the 100 mg/kg OXC pre- and post-treated ischemia groups, morphological characteristics of GFAP-immunoreactive astrocytes was similar to that in the ischemia groups." (PMID 31627311, 2019). "Previously, it has been shown that GFAP immunoreactivity was decreased after ischemia in Cx43 knockout mice and after blocking Cx43 in a TBI model." (PMID 31194577, 2019). "In the obestatin treatment group, the percentage of GFAP-positive cells was lower than the ischemia group (32.5% ± 4.5, P<0.01)." (PMID 31231488, 2019). "The effect of the PCA treatment on activation of microglia and astrocyte after ischemia were detected by using the surface marker CD11b and GFAP at seven days after insult." (PMID 29747437, 2018). "As expected, GFAP+ cells displayed relatively larger cell bodies and thicker processes, typical of astrogliosis after ischemia." (PMID 29588470, 2018). "Glial fibrillary acidic protein (GFAP) immunolabeling showed marked astrocytosis around the acute area of infarction and within chronic areas of ischemia." (PMID 30482198, 2018). "In contrast, astrocytes in the middle layers of the cortex, while rich in glutamate transporters have very low levels of GFAP, even if dramatic increases of GFAP can occur in astrocytes after brain injury, toxicity or ischemia." (PMID 29615864, 2018). "Additional triple fluorescence labeling of Coll IV, WFA and glial fibrillary acidic protein (GFAP) demonstrated in the affected tissue from mice and rats also fragmented astrocytes at 1 day after ischemia onset." (PMID 28860977, 2017). "In our experiment, many SDF-1α positive cells were co-labeled with GFAP staining after focal ischemia." (PMID 29228630, 2017). "In the ischemia and the ranibizumab groups, processes of radially oriented Müller cells also displayed GFAP-positive immunoreactivity." (PMID 28800629, 2017). "Statistical analysis of the GFAP and CD11b signals indicated that in the Sac-1004-ischemia group, glial activation was significantly attenuated compared with that in the vehicle-ischemia group." (PMID 28645333, 2017).
ischemia (continued). "When retinas are subjected to ischemia and preadministrated with vehicle, enhanced vimentin/GFAP immunoreactivity was found to be present simultaneously with the reduction in b-wave amplitude." (PMID 28709426, 2017). "Exercise‐treatment significantly decreased ramified GFAP‐immunoreactive astrocytic at days 7 and 14 post‐ischemia." (PMID 29201553, 2017). "Astrocytes respond to various forms of CNS injury such as infections, ischemia or neurodegenerative diseases through a process referred to as reactive astrogliosis and often characterized by an increase in GFAP expression." (PMID 27435172, 2016). "In the ischaemia groups, GFAP-immunoreactive astrocytes exhibited abnormal thorn-shaped and thread-like morphology in the hippocampal CA1 region along with a large amount of cytoplasm." (PMID 25781353, 2015). "Strong GFAP expression can be also a sign of reactive astrogliosis – a response to brain trauma, infection, ischemia, or neurodegenerative disorders where astrocytes strongly proliferate and undergo molecular and morphological changes." (PMID 25969464, 2015). "Hippocampal GFAP was also significantly elevated, while Bcl-2 and sirtuin 1 decreased significantly in response to ischemia." (PMID 26594596, 2015). "Morphologically, GFAP+ astrocytes in the penumbra experienced significant changes over time after ischemia." (PMID 24886391, 2014). "Astrocytes can exhibit enhanced Ca2+ signaling and are known to become reactive over time after ischemia as characterized by an excessive expression of GFAP (i.e., astrogliosis), and eventually form a glial scar surrounding the area of the ischemic core." (PMID 24886391, 2014). "In a preclinical model of ischemia, Li and colleagues demonstrated a protective role of astrocytes by knocking out glial fibrillary acidic protein (GFAP) and vimentin." (PMID 23344061, 2013). "In this study, the number of GFAP-expressing cells increased following cerebral anoxia and ischemia; however, the number of GFAP-expressing cells decreased with an extended anoxia-ischemia time." (PMID 23408790, 2013). "Eight-minutes of ischemia followed by 14 days of reperfusion results in extensive loss of CA1 pyramidal neurons and an increase in GFAP-positive astrocytes and microglia/macrophages positive for Iba-1." (PMID 24223835, 2013). "In the vehicle-ischemia-group at 2 days post-ischemia, processes of GFAP+ astrocytes became slightly slender." (PMID 24073226, 2013). "We observed that the expression and binding to Sin3A of EF094477 were induced after ischemia by 6.8- and 2.4-fold, respectively, and GFAP expression was also induced concomitantly." (PMID 24063527, 2013). "In contrast, a marked decrease in GFAP-immunostaining was observed in the contralateral pathway, corresponding to the diabetic eye that received ischemia pulses." (PMID 23284834, 2012). "After ischemia, astrocytes displayed reactive changes in cortex and striatum of vehicle treated groups which are characterized by increasing the expression of glial fibrillary acidic protein (GFAP) and the number of GFAP-positive cells." (PMID 23166749, 2012). "We have previously shown that cPA significantly suppresses ischemia-induced delayed neuronal death and the accumulation of glial fibrillary acidic protein in the CA1 region of the rat hippocampus." (PMID 23251428, 2012). "The size of the ischemic lesion and the intensity of GFAP staining gradually decreased starting on the seventh day of ischemia, and 14 days after MCAo the lesion comprised approximately 25% of its original size." (PMID 22590616, 2012). "The up-regulation of nestin and GFAP in Müller glia cells indicated that the transgenic retina experienced a gliotic response that is likely to be triggered by ischemia due to the missing retinal vasculature." (PMID 22880002, 2012).